METTL14 (methyltransferase 14, N6-adenosine-methyltransferase non-catalytic subunit)
Diseases named in the same sentence as METTL14 in open-access papers (continued):
Sharing a sentence is not in itself a finding about the gene and the disease.
oncocytoma (1 paper, 2021). "Compared to normal renal tissue protein expression of all investigated methyltransferases was increased in oncocytoma (METTL3 P < .001, METTL4 P < 0,001, METTL14 P = .003, KIAA1429 P = .001, WTAP P = .001)." (PMID 35474700, 2021).
progeria (1 paper, 2020). "Thus, METTL14 overexpression seems to delay replicative senescence in normal fibroblasts and can rescue premature senescence in progeria." (PMID 32813328, 2020).
prostate adenocarcinoma (1 paper, 2022). "A comparative analysis of genetic alterations in METTL3, METTL14, WTAP and CBLL1 in primary prostate adenocarcinoma and metastatic PCa patients was undertaken." (PMID 36733939, 2022). "Analysis of publicly available PCa patient datasets identified that METTL3 and WTAP expression was higher in primary prostate adenocarcinoma than in non-malignant prostate tissue, whereas conversely, METTL14 expression was found to be significantly lower." (PMID 36733939, 2022). "It was found that METTL3 (p < .0001) and WTAP (p < .01) expression were significantly higher in primary prostate adenocarcinoma patient samples compared with non-malignant prostate tissue, whereas METTL14 expression was significantly lower (p < .01) in tumour compared with non-malignant tissue." (PMID 36733939, 2022). "Expression and sub-cellular localisation of METTL3, METTL14, WTAP and CBLL1 were confirmed using IHC in both non-malignant and primary prostate adenocarcinoma specimens." (PMID 36733939, 2022).
prostate tumor (1 paper, 2022). "To quantify METTL14 expression in PCa patients, we performed IHC staining on a tissue microarray containing prostate tumor tissue specimens (n = 49) and adjacent normal prostate tissue specimens (n = 11)." (PMID 35354789, 2022).
pulmonary tuberculosis (1 paper, 2022). A bacterial infection that affects the lungs and is caused by Mycobacterium tuberculosis. "The aim of the current study was to investigate the contributing role of gene variation and transcription levels among the m6A methyltransferases METTL3, METTL14, and WTAP in pulmonary tuberculosis (PTB)." (PMID 36569923, 2022).
rectal tumors (1 paper, 2021). "The significant up-regulation of YTHDF1, YTHDF2, and METTL3, and down-regulation of ALKBH5, YTHDC2, and METTL14 could be observed in the 6 rectal tumors (P < 0.05), indicating that these m6A regulators may be associated with progression of RC." (PMID 34149792, 2021).
rectum adenocarcinoma (1 paper, 2021). An adenocarcinoma arising from the rectum. "= 0.213, p=0.0119) in rectum adenocarcinoma (READ), while METTL14 expression was not significantly correlated with CD4+ T cell infiltration (cor." (PMID 34221955, 2021).
renal fibrosis (1 paper, 2025). A final common manifestation of a wide variety of chronic kidney diseases characterized by glomerulosclerosis and tubulointerstitial fibrosis. "further demonstrated that METTL14 knockdown protected against streptozotocin-induced renal lesions and renal fibrosis in DN mice by regulating the stability and expression of TUG1 through m6A modification." (PMID 41585810, 2025).
respiratory allergies (1 paper, 2023). "Our findings suggest that m6A regulators, particularly METTL14, play a crucial role in the development of respiratory allergic diseases and the infiltration of immune cells." (PMID 37328853, 2023). "Finally, we propose that the possible application of topical nasal methylprednisolone for the treatment of respiratory allergies is related to the regulation of METTL14, providing new ways of investigating the treatment of respiratory allergies." (PMID 37328853, 2023). "Therefore, we hypothesized that the expression of METTL14, METTL16, and RBM15B closely influences the pathogenesis of respiratory allergies in mast and Th2 cells." (PMID 37328853, 2023).
Sertoli Cell-Only Syndrome (1 paper, 2024). A type of male infertility in which no germ cells are visible in any of the biopsied SEMINIFEROUS TUBULES (type I) or in which germ cells are present in a minority of tubules (type II). "Interestingly, a much more profound defect in spermatogenesis was observed upon Vasa-Cre mediated Mettl3 or Mettl14 deletion, as SSCs were affected and germ cell development was arrested at the zygotene-like stage, exhibiting the Sertoli cell-only syndrome phenotype in adults." (PMID 39030605, 2024).
severe combined immunodeficiency (1 paper, 2022). Severe combined immunodeficiency (SCID) comprises a group of rare monogenic primary immunodeficiency disorders characterized by a lack of functional peripheral T lymphocytes resulting in early-onset severe respiratory infections and failure to thrive. "After METTL14 knockdown GSCs transplanted into immunodeficiency non‐obese diabetes/severe combined immunodeficiency (NOD/SCID) mice, it was found that METTL14 depletion results in significant tumor progression initiated by GSCs in the cerebra of the mice." (PMID 34904301, 2022).
spinal cord injury (1 paper, 2023). Penetrating and non-penetrating injuries to the spinal cord resulting from traumatic external forces (e.g., WOUNDS, GUNSHOT; WHIPLASH INJURIES; etc.). "This study offers compelling evidence for METTL14-mediated m6A modification of UBR1 mRNA in modulating neuron autophagy and apoptosis in spinal cord injury (SCI), which may provide novel targets for modern SCI therapies." (PMID 37094938, 2023).
spinal muscular atrophy (1 paper, 2025). A motor neuron disease that affect the muscles, and characterized by muscle weakness and atrophy resulting from progressive degeneration and irreversible loss of the anterior horn cells in the spinal cord (i.e., lower motor neurons) and the brain stem nuclei. "Mutations in the SMN Tudor domain identified in spinal muscular atrophy (SMA) disrupt its interaction with METTL14 and reduce m6A levels in patient-derived fibroblasts, linking m6A dysregulation to SMA pathology." (PMID 41053315, 2025).
status epilepticus (1 paper, 2025). Status epilepticus is defined as a continuous seizure lasting more than 30 min, or two or more seizures without full recovery of consciousness between any of them. "The upregulation of METTL3 and METTL14 in hippocampus was demonstrated in epileptic rats at 8 and 12 weeks after status epilepticus induced by pilocarpine." (PMID 40534269, 2025).
stress-related disorder (1 paper, 2024). Stress-related disorders are mental health disorders that are a result of an atypical response to both short and long-term anxiety due to physical, mental, or emotional stress. "Moreover, previous studies showed that not only METTL3 but also METTL14 plays a crucial role in synaptic plasticity and stress-related disorders such as depressive behavior." (PMID 38453794, 2024).
testicular cancer (1 paper, 2020). A primary or metastatic malignant neoplasm that affects the testis. "In this review, we summarize the current research results for METTL3 and METTL14 and identify potential pathways involving these enzymes in kidney, bladder, prostate, and testicular cancer." (PMID 32765970, 2020). "From the limited studies available, we found that METTL3 and METTL14 have different expression patterns in four types of urological cancer (kidney, bladder, prostate, and testicular cancer)." (PMID 32765970, 2020).
tongue cancer (1 paper, 2024). A malignant neoplasm affecting the tongue. "Results demonstrated elevated expression of METTL14 or LIS1 in tongue cancer tissues." (PMID 38528591, 2024). "Immunohistochemistry experiment findings revealed elevated expression of METTL14 and LIS1 in tongue cancer patients compared to normal tissues." (PMID 38528591, 2024). "The results of human immunohistochemistry indicated that there is high expression of METTL14 and LIS1 in tongue cancer tissues compared to normal tissues." (PMID 38528591, 2024).
tuberculosis (1 paper, 2024). A chronic, recurrent infection caused by the bacterium Mycobacterium tuberculosis. "Together, these data demonstrate that EsxB is required for the pathogenesis of M. tuberculosis via inhibiting phosphorylation of METTL14-mediated anti-TB immunity." (PMID 38548762, 2024). "Furthermore, the deletion of Mettl14 dramatically impaired the anti-TB immunity as indicated by increased bacteria burden and pathological damage in the lung of M. tuberculosis-infected mice." (PMID 38548762, 2024).
Ureteral obstruction (1 paper, 2021). Obstruction of the flow of urine through the ureter. "However, in an animal model of AKI induced by unilateral ureteral obstruction (UUO) operation, m6A methylation in adult mouse kidneys was found to decrease and showed a similar change of the expressions of Mettl3 and Mettl14." (PMID 34307448, 2021).
urothelial carcinoma (1 paper, 2022). A malignant neoplasm derived from the transitional epithelium of the urinary tract (urinary bladder, ureter, urethra, or renal pelvis). "Because UMUC3 cell line showed a high relative expression s of METTL14, and it represents invasive urothelial carcinoma, an aggressive form of the disease, we decided to proceed with knockdown of this player in this specific cell line." (PMID 35048498, 2022).
tumor (393 papers, 2017 to 2026). "Increasing evidence suggests that dysfunction of PUS family members, similar to mutations in m6A methyltransferases such as METTL3 and METTL14, is closely associated with tumour initiation, progression, and immune evasion." (PMID 41496500, 2026). "It has been shown that in hepatocellular carcinoma, down-regulation of METTL14 and m6A expression is significantly associated with the high metastatic ability of tumours and the prognosis of patients." (PMID 40356909, 2025). "The loss of RNA N6-adenosine methyltransferase METTL14 in tumor-associated macrophages (TAMs) can stimulate tumor formation and impair CD8+ T cell function." (PMID 40271153, 2025). "METTL14 functions as a tumor suppressor in HCC and is strongly associated with the patient prognosis." (PMID 40290127, 2025). "METTL14 stimulates the expression of the tumour development and progression-associated protein seven in absentia homologue 2 (Siah2)." (PMID 40356909, 2025). "For instance, the HBV-encoded HBx protein recruits the METTL3/METTL14 complex to chromatin regions of tumour suppressors such as PTEN, facilitating their destabilization via YTHDF2 binding and promoting oncogenic PI3K – AKT signalling." (PMID 40793828, 2025). "IHC analysis of ~2500 BCa tumour specimens revealed an association of increased METTL14 and CBLL1 with favourable clinical outcomes in BCa and increased METTL3 expression with poor clinical outcomes in hormone receptor negative BCa." (PMID 41310336, 2025). "Specifically, macrophage-specific METTL14 deficiency can trigger significant functional impairment in tumor-infiltrating CD8+ T cells, characterized by compromised effector cytokine production and the marked upregulation of exhaustion-associated checkpoints." (PMID 40986143, 2025). "Conversely, in prostate cancer, elevated levels of m6A regulators, such as the m6A writer METTL14, are associated with low tumor heterogeneity and reduced neoantigen levels." (PMID 40176140, 2025). "Initially, in mice that underwent subcutaneous injection of these cells, over‐expression of ZFP14 resulted in lower tumour volumes and weights, while deficiency of METTL14 produced an opposite effect which was reversed by augmenting ZFP14." (PMID 39936533, 2025). "METTL14, a key component of the m6A methyltransferase complex, has been implicated in various cancers, exerting a significant role in tumour progression." (PMID 39021049, 2024). "Taken together, circSTX6 is closely associated with m6A and is negatively correlated with METTL14 in HCC tumour tissues." (PMID 37877357, 2023). "Since tumor metastasis and proliferation are closely associated with cancer stem cell properties, we investigate the effect of METTL14 on microsphere formation ability, which indicate cancer stem cell properties." (PMID 37283789, 2023). "Consistent with its anticancer effects in CRC cells, METTL14 in tumor-associated macrophages can also impede CRC growth." (PMID 37152066, 2023). "METTL14 was also confirmed to be reduced and associated with a tumour‐suppressing effect in colorectal cancer (CRC)." (PMID 36162823, 2023). "In ccRCC tissues, m6A writer METTL14 was downregulated and low level of METTL14 was negatively associated with the prognosis, stage, and ccRCC tumor grade." (PMID 37069649, 2023). "In fact, the loss of METTL3 or METTL14 enhances the interaction between the tumor and the immune system through the IFN-γ-STAT1-IRF1." (PMID 37427112, 2023). "Recently, C1Q+ TAMs have been reported to influence CD8+ T cell enrichment in tumors and Mettl14 or Ythdf2 deficiency in TAMs impedes tumor eradication by reducing cytotoxic T cell infiltration and encourage the accumulation of defective CD8+ T cells." (PMID 35538548, 2022). "The metastasis in vivo assay validated the impediment of BCa tumor metastasis caused by the elevation of METTL14 expression based on the reduced number of metastatic nodules." (PMID 36288387, 2022).
tumor (continued). "METTL14 is a major gene for aberrant m6A modification that is downregulated and can act as a poor element for recurrence-free survival associated with tumor metastasis in HCC." (PMID 36120301, 2022). "Knockdown of circORC5 repressed the colony formation and invasive capabilities, and attenuated METTL14 loss-induced tumor promoting effects in GC cells." (PMID 35164771, 2022). "According to the previous studies, the loss of METTL14 in tumor-associated macrophages promotes tumor growth and SUMOylation of the m6A-RNA methyltransferase influences its function." (PMID 35164771, 2022). "Nonetheless, the same authors showed increased METTL14 expression in patients with advanced stage of this malignancy, associating METTL14 overexpression with tumor aggressiveness." (PMID 35048498, 2022). "Approximately 70% of tumor samples in EC were previously reported to exhibit reduced m6A levels, primarily due to a loss-of-function METTL14 mutation at the R298P site and activation of the AKT pathway to enhance EC proliferation and tumorigenesis." (PMID 34230220, 2021). "Mettl3- or Mettl14-deficient tumors increased cytotoxic tumor-infiltrating CD8+ T cells and elevated secretion of IFN-c, Cxcl9, and Cxcl10 in tumor microenvironment in vivo." (PMID 34804948, 2021). "It has been reported that cytotoxic tumor-infiltrating CD8+ T cell is increased in METTL3 or METTL14 deficient tumor." (PMID 34616403, 2021). "The impacts of METTL14-associated m6A regulatory mechanisms on OC is complex and may exhibit both pro- and tumor suppressor potential, dependent upon the specific molecular and cellular context." (PMID 39904996, 2025). "Contextual variables such as tumor stage, mutational burden, and microbiome composition may further modulate METTL14 functions, yet remain underexplored in current research." (PMID 41164187, 2025). "Moreover, 2‐DG and 3‐BP, as well as SLC2A3 and PGAM1 down‐regulation, reversed the acceleration of tumor growth caused by METTL14 knockdown." (PMID 36794620, 2023). "In addition, the expression of circSTX6 in tumour tissues was negatively associated with METTL14 and ATF3 but positively correlated with circSTX6‐144aa." (PMID 37877357, 2023). "Moreover, decreased METTL14 expression was tightly associated with tumor lymph node metastasis, distant metastasis, and pathologic stage." (PMID 37283789, 2023). "And we found that decreased METTL14 level was tightly associated with tumor stages of CRC." (PMID 35974338, 2022). "Also, METTL14 deficiency in macrophages inhibited the anti-tumor function of CD8+ T cells and promoted tumor growth." (PMID 35296338, 2022). "To further investigate the mechanism underlying how METTL14 promotes tumor progression and identify its downstream targets in PCa, we conducted RNA-sequencing (RNA-seq) and Methylated RNA immunoprecipitation sequencing (MeRIP-seq) using shNC and shMETTL14 DU145 cells." (PMID 35354789, 2022). "Furthermore, in vivo experiments suggested that METTL3- or METTL14-deficient tumors were associated with increased abundance of cytotoxic tumor-infiltrating CD8+ T cells and significantly enhanced the secretion of IFN-γ, CXCL9, and CXCL10 in TME." (PMID 35692505, 2022). "Despite the normal 1:1 ratio formation between METTL3 and METTL14 in healthy cells, gene mutations, abnormal regulation, or changes in environmental factors during the tumor development process may disrupt this balance, resulting in differences in their expression and function." (PMID 38965238, 2024). "Furthermore, in vivo, METTL14 knockdown caused tumor size reduction." (PMID 35048498, 2022). "A mutation in METTL14 could facilitate tumour proliferation via the AKT signalling pathway." (PMID 35814454, 2022). "Functionally, METTL14 depletion promoted HUVEC tube formation in vitro and augmented tumor angiogenesis in vivo, effects mechanistically linked to VEGFA upregulation." (PMID 42213490, 2026).